MIR1208 (microRNA 1208)
Synonyms: hsa-mir-1208; MIRN1208
Gene: MicroRNA gene on chromosome 8 (128,150,116 to 128,150,188, forward strand). Ensembl gene ENSG00000221261.
Gene Ontology:
Biological process: miRNA-mediated post-transcriptional gene silencing
Cellular component: RISC complex
Homologues: Orthologues: chimpanzee ptr-mir-1208 (97% identical).
Diseases named in the same sentence as MIR1208 in open-access papers:
MIR1208 is named in the same sentence as 1 disease in open-access papers, as found by Europe PMC text mining. Sharing a sentence is not in itself a finding about the gene and the disease.
MIR1208 shares sentences with these, for which no sentence is quoted: Obesity (1 paper).